CIART (circadian associated repressor of transcription)
Description:
Transcriptional repressor which forms a negative regulatory component of the circadian clock and acts independently of the circadian transcriptional repressors: CRY1, CRY2 and BHLHE41. In a histone deacetylase-dependent manner represses the transcriptional activator activity of the CLOCK-BMAL1 heterodimer. Abrogates the interaction of BMAL1 with the transcriptional coactivator CREBBP and can repress the histone acetyl-transferase activity of the CLOCK-BMAL1 heterodimer, reducing histone acetylation of its target genes. Rhythmically binds the E-box elements (5'-CACGTG-3') on circadian gene promoters and its occupancy shows circadian oscillation antiphasic to BMAL1. Interacts with the glucocorticoid receptor (NR3C1) and contributes to the repressive function in the glucocorticoid response (By similarity).
Synonyms: Chrono; C1orf51; BC017397; GM129
Tractability: No criterion of Open Targets' tractability assessment is met for any kind of drug.
Gene: Protein-coding gene on chromosome 1 (150,282,543 to 150,287,093, forward strand). Ensembl gene ENSG00000159208.
Subcellular location: Nucleus; Nucleus, PML body
Subcellular location (Human Protein Atlas): Nucleoplasm
Gene Ontology:
Molecular function: protein binding; E-box binding; RNA polymerase II cis-regulatory region sequence-specific DNA binding; transcription cis-regulatory region binding
Biological process: circadian regulation of gene expression; locomotor rhythm; negative regulation of DNA-templated transcription
Cellular component: nucleus; PML body
Genetic constraint (gnomAD): Loss-of-function variants: 7 observed, 21.69 expected, observed/expected ratio (o/e) 0.32, 90% interval 0.18 to 0.61. The upper end of that interval is the gene's LOEUF score, 0.61, which puts it in group 2 of 6, group 1 being the genes least tolerant of losing a copy. Missense variants: 440 observed, 492.08 expected, observed/expected ratio (o/e) 0.89, 90% interval 0.83 to 0.97. Synonymous variants: 163 observed, 181.42 expected, observed/expected ratio (o/e) 0.9, 90% interval 0.79 to 1.02.
Homologues: Orthologues: chimpanzee CIART (99% identical), macaque CIART (97% identical), pig CIART (84% identical), dog CIART (83% identical), rabbit CIART (82% identical), mouse Ciart (77% identical), rat Ciart (76% identical), tropical clawed frog ciart (35% identical), zebrafish ciarta (25% identical).
Diseases named in the same sentence as CIART in open-access papers:
CIART is named in the same sentence as 7 diseases in open-access papers, as found by Europe PMC text mining. Sharing a sentence is not in itself a finding about the gene and the disease. The quoted sentences say what the papers report.
influenza (1 paper, 2023). An acute viral infection of the respiratory tract, occurring in isolated cases, in epidemics, or in pandemics; it is caused by serologically different strains of viruses (influenzaviruses) designated A, B, and C, has a 3-day incubation period, and usually lasts for 3 to 10 days. "CIART expression was also upregulated following influenza infection of ALOs, AWOs and CMs, indicating that the induction of CIART is not specific to SARS-CoV-2 infection." (PMID 36918693, 2023). "We infected hPSC-ALOs, -AWOs and -CMs with influenza to test whether CIART upregulation is specific to SARS-CoV-2 infection." (PMID 36918693, 2023).
cancer (2 papers, 2020 to 2022). A tumor composed of atypical neoplastic, often pleomorphic cells that invade other tissues. "Among them, certain rhythm genes such as DBP, CRY2, and CIART are protective effectors for the prognosis of most cancers, whereas certain rhythm genes such as TIMELESS and SERPINE1 are risk factors for the prognosis of most cancer." (PMID 31927791, 2020). "Genes containing AS events associated with overall survival are known components of cancer-related pathways, including regulation of transcription (E2F4, ZNF730, GPBP1, POLR2J, SP2, and CIART), cell cycle (E2F4 and GTSE1), or cell-cell adhesion (CEACAM1, MMP14, EPS8L2, AP3D1, AFDN, and PAK4)." (PMID 35044822, 2022).
infection (1 paper, 2023). The state of being infected such as from the introduction of a foreign agent such as serum, vaccine, antigenic substance or organism. "Systematic infection of a human multi-organoid system shows that deficiency in the host factor CIART impairs SARS-CoV-2 infection through downregulation of the RXR pathway and subsequent impairment of fatty-acid synthesis." (PMID 36918693, 2023). "As seen in hPSC-CMs and hPSC-AWOs, CIART−/− hPSC-ALOs were highly resistant to infection, as determined by qRT-PCR and immunofluorescence staining in SP-B+SP-C+ alveolar type 2 cells." (PMID 36918693, 2023).
CIART also shares sentences with these, for which no sentence is quoted: asthma (1 paper); astrocytoma (1); bipolar disorder (1); schizophrenia (1).